LONP1 (lon peptidase 1, mitochondrial)
Description:
ATP-dependent serine protease that mediates the selective degradation of misfolded, unassembled or oxidatively damaged polypeptides as well as certain short-lived regulatory proteins in the mitochondrial matrix. Endogenous substrates include mitochondrial steroidogenic acute regulatory (StAR) protein, DELE1, helicase Twinkle (TWNK) and the large ribosomal subunit protein MRPL32/bL32m. MRPL32/bL32m is protected from degradation by LONP1 when it is bound to a nucleic acid (RNA), but TWNK is not. In addtion to its protease activity, has also an ATP-dependent protein folding chaperone activity and functions in mitochondrial protein folding. Participates in the regulation of mitochondrial gene expression and in the maintenance of the integrity of the mitochondrial genome. Binds to mitochondrial promoters and RNA in a single-stranded, site-specific, and strand-specific manner. May regulate mitochondrial DNA replication and/or gene expression using site-specific, single-stranded DNA binding to target the degradation of regulatory proteins binding to adjacent sites in mitochondrial promoters.
Synonyms: LONP; Lon; PRSS15; LonHS; hLON; PIM1; CODASS
Tractability: Small molecule: a structure with a bound ligand is known; it has a high-quality binding pocket. PROTAC: ubiquitination databases record sites on it; its protein half-life has been measured; a small molecule that binds it is known.
Target class: Enzyme; Hydrolase
Gene: Protein-coding gene on chromosome 19 (5,691,834 to 5,720,572, reverse strand). Ensembl gene ENSG00000196365.
Subcellular location: Mitochondrion matrix
Subcellular location (Human Protein Atlas): Mitochondria; Cytosol; Nucleoplasm
Pathways (Reactome):
Cellular responses to stimuli: Mitochondrial unfolded protein response (UPRmt)
Metabolism of proteins: Mitochondrial protein degradation
Gene Ontology:
Molecular function: ADP binding; ATP binding; ATP-dependent peptidase activity; ATP-dependent protein folding chaperone; DNA polymerase binding; G-quadruplex DNA binding; identical protein binding; mitochondrial promoter sequence-specific DNA binding; protein binding; sequence-specific DNA binding; serine-type endopeptidase activity; single-stranded RNA binding; single-stranded DNA binding; ATP hydrolysis activity; insulin receptor substrate binding; PH domain binding
Biological process: 'de novo' protein folding; cellular response to oxidative stress; mitochondrial protein catabolic process; mitochondrion organization; oxidation-dependent protein catabolic process; protein catabolic process; response to hypoxia; protein quality control for misfolded or incompletely synthesized proteins; chaperone-mediated protein complex assembly; protein-containing complex assembly; proteolysis; response to aluminum ion; response to hormone
Cellular component: membrane; mitochondrial matrix; mitochondrial nucleoid; mitochondrion
Genetic constraint (gnomAD): Loss-of-function variants: 33 observed, 98.41 expected, observed/expected ratio (o/e) 0.34, 90% interval 0.25 to 0.45. The synonymous counts are far from expectation, so gnomAD's model fits this gene poorly and the ratio says little. Missense variants: 1,335 observed, 1,352 expected, observed/expected ratio (o/e) 0.99, 90% interval 0.94 to 1.03. Synonymous variants: 781 observed, 600.88 expected, observed/expected ratio (o/e) 1.3, 90% interval 1.23 to 1.38.
Gene-disease validity (ClinGen):
ClinGen rates the evidence that LONP1 causes each of these diseases.
Leigh syndrome (autosomal recessive): Limited. A progressive neurological disease defined by specific neuropathological features associating brainstem and basal ganglia lesions.
Homologues: Orthologues: chimpanzee LONP1 (99% identical), macaque LONP1 (98% identical), dog LONP1 (94% identical), pig LONP1 (92% identical), guinea pig LONP1 (89% identical), rat Lonp1 (88% identical), mouse Lonp1 (88% identical), tropical clawed frog lonp1 (77% identical), zebrafish lonp1 (76% identical), Drosophila melanogaster Lon (60% identical), Caenorhabditis elegans lonp-1 (50% identical). Paralogues in human: LONP2 (31% identical).
Diseases named in the same sentence as LONP1 in open-access papers:
LONP1 is named in the same sentence as 119 diseases in open-access papers, as found by Europe PMC text mining. Sharing a sentence is not in itself a finding about the gene and the disease. The quoted sentences say what the papers report.
CODAS syndrome (21 papers, 2015 to 2025). Codas syndrome is a multiple congenital anomalies syndrome characterized by Cerebral, Ocular, Dental, Auricular and Skeletal anomalies. "Homozygous and compound heterozygous mutations in LONP1 cause CODAS syndrome (MIM #600373), characterised by cerebral, ocular, dental, auricular and skeletal anomalies." (PMID 40857737, 2025). "Among these proteases, LONP1 mutations have been associated with CODAS syndrome (cerebral, ocular, dental, auricular, skeletal syndrome), a disorder characterized by multisystem malfunctions." (PMID 39221030, 2024). "The Lonp1 mutation was initially identified in the Cerebral, Ocular, Dental, Auricular, Skeletal (CODAS) syndrome." (PMID 38625722, 2024). "Previous studies have suggested that the complex multisystemic and developmental condition CODAS syndrome is caused by recessively inherited, pathogenic abnormalities in LonP1 gene." (PMID 36684615, 2023). "Pathogenic Lonp1 mutations are associated with CODAS syndrome, a rare multisystem disorder affecting the development of the cerebral, ocular, dental, auricular, and skeletal systems." (PMID 36978846, 2023). "Typically, biallelic variants in LONP1 cause cerebral, ocular, dental, auricular, and skeletal anomalies (CODAS) syndrome (MIM#600,373), a neonatal multisystem disorder where variants are located in the ATP-dependent protease LON-binding domain." (PMID 35699875, 2022). "The binding site of CDDO derivatives was validated by amino acid substitutions that increased LonP1 inhibition and also by a pathogenic mutation that causes cerebral, ocular, dental, auricular and skeletal (CODAS) syndrome, which ablated inhibition." (PMID 35151690, 2022). "The first disease identified to be caused by biallelic LONP1 missense mutations was CODAS syndrome, a rare developmental disorder characterized by cerebral, ocular, dental auricular and skeletal anomalies." (PMID 35151690, 2022). "Mutations of LONP1 gene are associated with Cerebral Ocular Dental Auricular Skeletal Anomalies Syndrome (CODAS), a complex multisystemic and developmental disorder." (PMID 35760833, 2022). "For example, mapping known CODAS syndrome-associated mutations of human LONP1 onto our structure of proteolytically active LONP1Bz highlights their position at interfaces between ATPase domains." (PMID 34050165, 2021). "LONP1 is a nuclear-encoded mitochondrial protease crucial for organelle homeostasis; mutations of LONP1 have been associated with Cerebral, Ocular, Dental, Auricular, and Skeletal anomalies (CODAS) syndrome." (PMID 32521756, 2020). "Point mutations of LonP1 in humans lead to the development of a rare disease named CODAS syndrome (cerebral, ocular, dental, auricular, and skeletal syndrome) with failure of oxidative phosphorylation." (PMID 31547314, 2019). "Recessively inherited, pathogenic defects in LonP1 have been previously reported to underlie cerebral, ocular, dental, auricular and skeletal anomalies (CODAS) syndrome, a complex multisystemic and developmental disorder." (PMID 29518248, 2018). "Previous reports have linked pathogenic LonP1 mutations to CODAS syndrome." (PMID 36684615, 2023). "Biallelic mutations in the chromosomal gene encoding human LonP1 cause CODAS syndrome." (PMID 35151690, 2022). "However, most autosomal recessive mutations in LONP1 are associated with the CODAS syndrome, which has broader symptoms than typical mitochondrial diseases." (PMID 34400774, 2021). "Mutations of LonP1 in humans lead to a rare multi-system developmental disorder—CODAS syndrome." (PMID 31547314, 2019). "Furthermore, a c.2014C > T, p.(Arg627Cys) LONP1 variant has also been implicated in causing both CODAS syndrome and isolated paediatric cataracts." (PMID 29518248, 2018). "Recently, CODAS syndrome, a multi-system developmental disorder characterized by cerebral, ocular, dental, auricular, and skeletal anomalies, was associated with mutations of LONP1, encoding mitochondrial AAA+ Lon Protease45." (PMID 27417535, 2016).
CODAS syndrome (continued). "LONP1 deficiency (LONP1, autosomal recessive inheritance, MIM #605490) causes Cerebral Ocular Dental Auricular Skeletal Anomalies Syndrome (CODAS), a complex multisystemic and developmental disorder." (PMID 38872485, 2025).
melanoma (13 papers, 2018 to 2026). A malignant, usually aggressive tumor composed of atypical, neoplastic melanocytes. "More recently, LonP1 has been implicated in the control of metabolic networks in mitochondria in melanoma cells, and in hypoxic adaptation in glioma cells." (PMID 30038898, 2018). "In melanoma cells, LONP1 overexpression disrupted the assembly and function of ETC complex I, leading to the down-regulation of mitochondrial respiration and up-regulation of the glycolytic pathway, which promoted cell proliferation and invasion." (PMID 40332105, 2025). "LONP1 over-expression results in impaired complex I assembly in melanoma cells, upregulation of NDUFB6,8,10 and 11, and downregulation of NDUFV1, NDUFV2, NDUFS3 and NDUFS7." (PMID 38263327, 2024). "LONP1 silencing leads to reduced proliferation in melanoma, colorectal cancer, and pancreatic cancer." (PMID 36768800, 2023). "Some studies have demonstrated that LONP1 expression is significantly increased in melanoma and is related to changes in the metabolic mode of melanoma cells." (PMID 37221594, 2023). "Overexpression of LONP1 promotes the progression of melanoma, whereas its knockdown inhibits tumour growth and migration." (PMID 37221594, 2023). "LONP1, another key protease involved in UPRmt, is upregulated in various cancers, including melanoma, colorectal cancer, and pancreatic cancer." (PMID 36768800, 2023). "For example, melanoma cells with knocked-down LonP1 have reduced levels of complexes I, II, and IV, which significantly compromise cellular respiration." (PMID 36362158, 2022). "In melanoma cells, both the overexpression and knockdown of LonP1 have been found to contribute to a decrease in OXPHOS and increase in glycolysis, although changes in the mitochondrial complexes varied." (PMID 36362158, 2022). "High expression of LONP1 correlates with reduced overall survival in neuroblastoma, breast cancer, colorectal cancer, renal cell carcinoma, and metastatic cohorts of melanoma." (PMID 35864539, 2022). "The pro-tumor effects of LONP1 can be partially attributed to LONP1-mediated regulation of Bcl-2 in melanoma, cyclin D1 in pancreatic cancer, and β-catenin in colorectal cancer." (PMID 35864539, 2022). "More recently, LONP1 has been involved in the control of mitochondrial metabolic networks in melanoma cells as well as being involved in hypoxia adaptation in glioma cells." (PMID 36190692, 2022). "In melanoma, LONP1 knockdown inhibits the formation of OXPHOS Complexes I and III and reduces the activities of OXPHOS Complexes I, II, and III." (PMID 35864539, 2022). "Knockdown of LONP1 leads to reduced proliferation in melanoma, colorectal cancer, pancreatic cancer, and PCa cells." (PMID 35864539, 2022). "In ClpP−/− mice, we previously observed an accumulation of mtDNA, whereas mtDNA was lower upon knockdown of LonP1 in B16F10 melanoma cells." (PMID 31547314, 2019). "Dysregulation of LONP1 has been associated with colon cancer and melanoma, but has not been studied in the context of AML." (PMID 41289019, 2026). "LONP1 is upregulated in melanoma, prostate cancer, pancreatic cancer, and colorectal cancer." (PMID 35864539, 2022). "However, if the protein expression of LONP1 is too low, it may lead to mitochondrial dysfunction, thereby promoting the occurrence and development of melanoma." (PMID 37221594, 2023). "The most significant differences in melanoma are NOMO1, PIGT, VKORC1, PDIA5 and DDX11, and the most significant differences in uterine cancer are CTU2, EMC8, TUBG1, CLPP and LONP1." (PMID 34951103, 2022). "For example, the Lon protease degrades oxidized mitochondrial proteins and inhibition of LONP1 has anti‐cancer activity in colorectal cancer and melanoma, although inhibiting LONP1 does not reduce the growth of AML cells." (PMID 32761807, 2020).
melanoma (continued). "We found that although LonP1 siRNA was not able to interfere with cell movement, pharmacological inhibition of LonP1 was able to negatively affect the motility of both fibrosarcoma and melanoma cells." (PMID 35456042, 2022).
colorectal cancer (8 papers, 2018 to 2024). A primary or metastatic malignant neoplasm that affects the colon or rectum. "A study by our research group highlighted Lonp1 presence in the nucleus of colorectal cancer cells undergoing heat shock and its association with enhanced expression of stress response genes, suggesting that Lonp1 is involved in cellular stress response." (PMID 36978846, 2023). "LonP1 deficiency has been found to protect mice from chemically-induced colorectal cancer in vivo." (PMID 36362158, 2022). "LonP1 deficiency protects mice from chemically-induced colorectal cancer." (PMID 36362158, 2022). "In other words, LONP1 deacetylation inhibits its function in promoting metabolism in colorectal cancer cells and inhibits cell proliferation and tumor growth." (PMID 36739437, 2023). "For example, Lonp1 overexpression in cancer cells, such as colorectal cancer, Oral Squamous Cell Carcinoma, and Non-Small Lung Cancer, promotes cell proliferation, apoptotic resistance to stress, and neoplastic transformation." (PMID 36978846, 2023). "Mitochondrial Lon protease (LonP1) is a multi-function enzyme that regulates mitochondrial functions in several human malignancies, including colorectal cancer (CRC)." (PMID 30038898, 2018).
glioma (7 papers, 2018 to 2025). A benign or malignant brain and spinal cord tumor that arises from glial cells (astrocytes, oligodendrocytes, ependymal cells). "Using gain- and loss-of-function genetic models, we discovered that LonP1 is both necessary and sufficient to drive BT317 drug sensitivity in established and patient-derived glioma stem-like cells by generating ROS and inducing apoptosis." (PMID 40088962, 2025). "Analogous phenomena have been noted in cancer cells, with LonP1-knockdown glioma and prostate cancer cells displaying a lowered OCR, accompanied with the reduced proliferation and increased death of tumor cells." (PMID 36362158, 2022). "Here, we present evidence that the dual inhibition of LonP1 and CT-L proteasome activity effectively induces ROS production, leading to apoptosis in malignant astrocytoma established cell lines and patient-derived glioma stem cell-like cultures." (PMID 40088962, 2025). "In addition, LonP1 knockdown reduces intracellular transport in the mitochondria of prostate cancer cells and impairs the resistance to hypoxia in glioma cells." (PMID 36362158, 2022). "The knockdown of LonP1 in bladder cancer, cervical cancer, prostate adenocarcinoma, and glioma cells induces a decline in mitochondrial respiratory function with reduced ATP production, and some cells exhibit the downregulation of both OXPHOS and glycolytic pathways." (PMID 36362158, 2022). "Moreover, elevated LONP1 expression is correlated with high glioma tumor grade and poor patient survival, and LONP1 silencing dramatically reduces glioma cell survival under hypoxic conditions." (PMID 35269393, 2022). "Here, we present evidence that the dual inhibition of LonP1 and Chymotrypsin-like (CT-L) proteasome activity effectively induces cellular reactive oxygen species (ROS) production, leading to apoptosis in malignant astrocytoma established cell lines and patient-derived glioma stem cell-like cultures." (PMID 40088962, 2025).